TNF (tumor necrosis factor)
Diseases named in the same sentence as TNF in open-access papers (continued):
Sharing a sentence is not in itself a finding about the gene and the disease.
hepatocellular carcinoma (continued). "Our findings suggested that autophagy conferred the TNF-α protection against serum starvation-mediated apoptosis of hepatocellular carcinoma cells, the mechanism involved with the activation of the TNF-α/ NF-κB /FHC signaling pathway." (PMID 24066693, 2013). "The basic objective of this study was to investigate the effects of TNF-α on the cell viability and apoptosis of hepatocellular carcinoma cells under serum starvation, and to identify the molecular mechanisms involved." (PMID 24066693, 2013). "TNF-α (10 ng/ml) attenuated serum starvation-induced apoptosis of hepatocellular carcinoma cells, and autophagy conferred this process." (PMID 24066693, 2013). "Effects of tocilizumab and infliximab (anti-TNF-α antibody) on cytokine-induced hepcidin expression in hepatoma cells were analyzed by quantitative real-time PCR." (PMID 24286116, 2013). "We also found that TNF-α inhibited both basal level and IL-6-induced hepcidin expressions in hepatoma cells." (PMID 24286116, 2013). "We tested this idea initially in the Huh7 hepatoma cell line, where we were able to demonstrate a dose-dependent inhibition of hepcidin expression following treatment with TNFα." (PMID 22675442, 2012). "It has been reported that the expression of LRAG in human hepatoma cells was induced by IL-6, IL-1β, and TNFα; and that the LRAG expression was enhanced by the induction of acute inflammation in mice." (PMID 22568928, 2012). "The HCV core protein has been shown to activate NF-κB, inducing resistance to TNF-α-induced apoptosis in hepatoma cells." (PMID 22922731, 2012). "Primary rat hepatocytes, HepG2-rNtcp cells (human hepatocellular carcinoma cells) or H-4-II-E cells (rat hepatoma cells) were exposed to glycochenodeoxycholic acid (GCDCA) or tumor necrosis factor-α (TNFα)/actinomycin D (ActD)." (PMID 22900098, 2012). "It was also shown to induce apoptosis of human hepatoma HepG2 cells through tumor necrosis factor-α (TNF-α) and interleukin (IL)-1β secretion, and to have cytotoxic activity in the human colon colorectal adenocarcinoma cell line Caco-2." (PMID 23135630, 2012). "For the first time we found that GSK3β was involved in mtDNA depletion in response to TNF-α in hepatoma cells." (PMID 22911714, 2012). "We found that HBx modulated IKKβ/TSC1/mTOR signaling and up-regulated cell proliferation and VEGF production in both unstimulated and TNF-α-stmulated hepatoma cells." (PMID 22848663, 2012). "Release of TNF alpha from Kupffer cells leads to hepatocyte cell death, regeneration and fibrosis that can lead to hepatocellular carcinoma." (PMID 21901081, 2011). "The regulatory mechanism of ATX by the key inflammatory component TNF-α/NF-κB axis was studied in human hepatoma cell lines." (PMID 20356387, 2010). "Alternatively, Gharavi and El-Kadi (2005) showed in murine hepatoma cell lines that Cyp1a1 is down-regulated by the proinflammatory cytokines interleukin 1β (Il-1β), IL-6, and tumor necrosis factor α in an AHR-dependent manner." (PMID 19165387, 2009). "In vitro studies in hepatoma cell lines illustrate the downregulation of Cyp3a11 exposed to the proinflammatory cytokines IL-6, IL-1β and TNF-α." (PMID 18059400, 2008). "TNF-α suppresses Bcl-2 in FaO rat hepatoma cells while it induces Bcl-2 in rat hippocampal neuron cells." (PMID 17570844, 2007). "To investigate whether pro-inflammatory stimuli regulate ACBP/DBI expression, we stimulated HepG2, a human hepatoma cell line, and peripheral blood mononuclear cells (PBMCs) from healthy human donors with lipopolysaccharide (LPS), IL-1β, and TNFα." (PMID 40867617, 2025). "It contributes to liver health by slowing hepatocellular carcinoma (HCC) progression, improves metabolic health by enhancing insulin sensitivity and reducing diabetes risk, and lowers inflammation by reducing oxidative stress and cytokines like IL-6 and TNF-α." (PMID 40718363, 2025).
hepatocellular carcinoma (continued). "MYDGF may promote tumor angiogenesis and macrophage infiltration in hepatocellular carcinoma, releasing inflammatory cytokines, including IL-6 and TNF-α, which accelerate tumor progression." (PMID 40539074, 2025). "Finally, translocation of p65 in CD81-negative hepatoma cells was markedly induced upon stimulation with TNFα or PMA." (PMID 38357447, 2024). "Furthermore, moving to hepatoma cells, we found overall increased basal levels of p65 and phosphorylated p65, even though independently of TNFα." (PMID 38357447, 2024). "TNF-α can also induce FoxMI expression to resist cell apoptosis in hepatocellular carcinoma." (PMID 37432179, 2023). "Also, increased amounts of inflammatory mediators such as TNF-α, C-reactive protein, and IL-6 have been found in the sera of hepatocellular carcinoma patients." (PMID 36430792, 2022). "On the other side, the progression of the cirrhosis and hepatocellular carcinoma could potentially be accelerated through the immunosuppression induced by TNF-α-inhibitors." (PMID 35203438, 2022). "To investigate whether TNF-α promotes Hepa1-6 cell proliferation in an inflammatory state, we measured the levels of the inflammatory hepatocellular carcinoma-related cytokine IL-6 in Hepa1-6 cells treated with 50 ng/ml TNF-α." (PMID 35676936, 2022). "TNFα and IFNγ upregulate FAT10, which increases susceptibility to inflammation-driven diseases like nonalcoholic fatty liver disease (NAFLD), non-alcoholic steatohepatitis (NASH), and hepatocellular carcinoma (HCC)." (PMID 36386217, 2022). "Furthermore, CatC promotes proliferation and metastasis in hepatocellular carcinoma by interacting with the tumor necrosis factor α (TNF‐α)/p38 MAPK signaling pathway." (PMID 35067006, 2022). "Indeed, we found that TNF-α dose-dependently promoted the proliferation of Hepa1-6 mouse hepatoma cells, with the highest proliferation observed at 50 ng/ml TNF-α." (PMID 35676936, 2022). "In the liver, TNF induces numerous biological responses such as hepatocyte apoptosis and necroptosis, liver inflammation and regeneration, and autoimmunity, but also progression to hepatocellular carcinoma." (PMID 35122118, 2022). "Moreover, TNF-α stimulates SREBP1 activation via a caspase-dependent pathway in HepG2 cells derived from hepatocellular carcinoma." (PMID 36500345, 2022). "In addition, we demonstrated that downregulation of TNFAIP1 induced the expression of pro-inflammatory cytokines IL-6 and IL-8 in TNFα-stimulated hepatocellular carcinoma cells through the activation of p38/JNK MAPK pathway via blocking RhoB degradation." (PMID 33553178, 2021). "In a previous study, we demonstrated that activation of the autophagic flux determines the lysosomal relocation of the cytoplasmic metallothioneins (MT), a class of iron-binding proteins, and grants rat hepatoma cells with a greater resistance to TNF-mediated cytotoxicity." (PMID 33809171, 2021). "Interestingly, overexpression of Gclc subunits has shown to protect pancreatic islets from oxidative stress, or attenuate TNF-induced mitochondrial injury and apoptosis in mouse hepatoma cells." (PMID 32942603, 2020). "On the other hand, the secreted IFN-gamma and TNF-alpha could further induce the high expression of NKG2D ligand in hepatoma cells so as to enhance the sensitivity of NKL-IL15 cells to target cells." (PMID 32075046, 2020). "In hepatoma cell line, palmitate increased IL-6 and TNF-α expressions and pJNK level." (PMID 31913329, 2020). "In liver cells or hepatoma cell lines (e.g., Huh-7 cells), TNFα and IL-1β induced by LPS only have minor effects on SOCS expression and their effects on GH resistance are mediated by reducing GHR gene transcription, probably through inhibition of Sp1/3 binding to GHR promoter." (PMID 32082258, 2020).
hepatocellular carcinoma (continued). "Aberrations in HNF4α functionality are known from the development of severe cirrhotic livers, alcoholic liver disease, tumor necrosis factor-α-induced hepatotoxicity, and hepatocellular carcinoma where HNF4α has an anti-proliferative effect and serves as a tumor suppressor." (PMID 30654452, 2019). "These compounds decreased the gene expression of tumor necrosis factor-alpha (TNF-α), interleukin-6 (IL-6) and interleukin-1beta (IL-1β) in lipopolysaccharide (LPS) induced inflammation in a hepatocellular carcinoma cell line (HepG2) in a dose-dependent manner." (PMID 31484451, 2019). "In addition, we also tested other inflammatory factors, such as IL-6 and TNFα, for their induction of PD-L1 expression on hepatoma cells." (PMID 31727135, 2019). "Furthermore, 96 can markedly inhibit LPS or TNF-α-induced activation of NF-κB through both inhibiting the phosphorylation of IκBα and p65 and preventing the P65 nuclear translocation to exhibit anti-hepatoma and anti-inflammatory activities." (PMID 31288582, 2019). "The data contain information related to the research article entitled “Profiling of promoter occupancy by the SND1 transcriptional coactivator identifies downstream glycerolipid metabolic genes involved in TNFα response in human hepatoma cells” (DOI: 10.1093/nar/gkv858)." (PMID 31667320, 2019). "In line with human evidence, deletion of both TRAF2 and RIP1 in liver parenchymal cells (LPC) leads to spontaneous development of hepatocellular carcinoma, which results from extensive hepatocyte apoptosis due to hyperactivation of caspase-8 but impaired NF-κB activation induced by TNFα." (PMID 30294322, 2018). "Examples of these include Cu/Zn-superoxide dismutase (SOD1) mutant-induced motoneuronal cell death, Cisplatin-induced apoptosis in NIH3T3 cells, UV-induced apoptosis in COS-1 cells, TIPE1- induced apoptosis in hepatocellular carcinoma cells, and TNF-α-induced apoptosis in endothelial cells." (PMID 29321004, 2018). "Moreover, hypoxia-mediated potentiation of TNF-α secretion has been observed for macrophages, osteoblasts, and human hepatocellular carcinoma cells." (PMID 30463908, 2018). "As determined in this latter cellular model, IFNβ directs STAT1 binding to a critical regulatory site within the murine iNOS promoter (−912 to −1,029 bp relative to the TSS), a process that, in Hepa1-6 hepatoma cells, demanded simultaneous pro-inflammatory signaling by IL-1β/TNFα." (PMID 28824623, 2017). "In our previous report, we had shown that the TNF-α could augment proliferation of mTregs through TNF-α/TNFR2 interaction in patients with hepatoma and colon cancer." (PMID 29127350, 2017). "Experiments are ongoing in our laboratory to determine whether CSP I-plus could increase other antitumor domains (e.g. interferon α, interleukin-24, tumor necrosis factor α, etc) homing to hepatocellular carcinoma cells and their biologic activity." (PMID 29075040, 2017). "Results of various other studies also show that, relative to normal healthy controls, a significant increase in circulating levels of TNF-α was observed in hepatocellular carcinoma patients, cervical neoplasia, epithelial ovarian cancer, prostate cancer, and renal cell carcinoma." (PMID 26881177, 2016). "NF-κB activation is required for the induction of MAT2A by TNF-α in hepatoma cells." (PMID 26418898, 2016). "To test this hypothesis, we firstly treated the hepatoma cells in vitro with inflammatory factor TNF-α." (PMID 26458400, 2015). "Overall, our findings uncover an unexpected large set of potential SND1 target genes and partners and reveal SND1 to be a determinant downstream effector of TNFα that contributes to support glycerophospholipid homeostasis in human hepatocellular carcinoma during inflammation." (PMID 26323317, 2015).
hepatocellular carcinoma (continued). "Moreover, studies have revealed that the levels of TNF-α and IL-6 are significantly increased in rats bearing hepatoma, which reflects an aggressive inflammatory response correlated with tumor induction." (PMID 24918094, 2014). "Importantly, preincubation of LPS-stimulated macrophage CM with anti-TNF-α reduced HCVpp infection to a comparable level observed with untreated hepatoma cells." (PMID 24259385, 2014). "Our observation that TNF-α promotes the entry of several pseudoviruses to polarized hepatoma cells suggests that TNF-α affects the function or distribution of several different classes of viral receptors, most likely through modulating membrane receptor trafficking." (PMID 24259385, 2014). "Importantly, this effect was not limited to HCV; TNF-α increased the permissivity of hepatoma cells to infection by Lassa, measles and vesicular stomatitis pseudoviruses." (PMID 24259385, 2014). "In addition, TNF-α up-regulated Ferritin heavy chain (FHC) transiently by NF-κB activation and FHC levels were correlated with the TNF-α-induced protection against serum starvation-mediated apoptosis of hepatocellular carcinoma cells." (PMID 24066693, 2013). "In addition, ginger extract (Zingiber officinale) significantly reduced the elevated expression of NF-κB and TNF-α in ethionine-induced hepatoma rats." (PMID 24015236, 2013). "Understanding the contribution of TNF-α-mediated cell survival may be relevant to the therapy of hepatocellular carcinoma." (PMID 24066693, 2013). "Our findings suggested that autophagy conferred the TNF-α protection against serum starvation-mediated apoptosis of hepatocellular carcinoma cells, the process involved with transactivation of NF-κB, up-regulation of anti-apoptotic FHC, suppression of reactive oxygen species and caspase." (PMID 24066693, 2013). "Moreover, overexpression of regucalcin has been shown to have a suppressive effect on TNF-α-induced apoptosis in human hepatoma HepG2 cells." (PMID 23670020, 2013). "To further assess the roles of TNF-α and IL-1β in the pathogenesis of RA-anemia and their effects on IL-6-induced hepcidin mRNA expression, we performed in vitro real-time RT-PCR assays using a hepatoma-derived cell line." (PMID 24286116, 2013). "IL-6 and TNF null mice have decreased production of hepatic lipid and macrophage infiltration when fed a high-fat diet, resulting in the suppression of steatohepatitis and hepatocellular carcinoma (HCC) formation." (PMID 27335818, 2013). "To determine whether IL-19 promotes the expression of TNF-α and IL-10, we analyzed the effect of IL-19 on the HepG2 human hepatoma cell line." (PMID 23468852, 2013). "Moreover, human hepatoma cells (HuH7) were used to study the effect of IL-6 and TNF-α on HJV mRNA expression." (PMID 22998440, 2012). "Serum Amyloid A is induced by TNF-α in mouse hepatocytes and it might be responsible for the inhibition that is consequent to TNF-α-stimulation of mouse primary hepatocytes or mouse hepatoma cell lines." (PMID 21394207, 2011). "Moreover, we explored the mechanism governing the expression of ATX in hepatoma cells and established a critical role of nuclear factor-kappa B (NF-κB) in basal and TNF-α induced ATX expression." (PMID 20356387, 2010). "HuH-7 cells, a human hepatoma cell line, were first transfected with the pEGFP-LD series of plasmids and treated with TNF-α at 24 h post-transfection for 2 h so that the EGFP-LD would behave like authentic LDAg and be translocated from the nucleus to cytoplasm after the TNF-α treatment." (PMID 19284884, 2009). "We treated human hepatoma cell line, HepG2 cells, with elevated physiological level (0.7 mM) of different types of FFAs (saturated, monounsaturated and polyunsaturated) “crossed” with 3 different levels of TNF-α, 0, 20 and 100 ng/ml for 24 h." (PMID 19052637, 2008). "For example, TGF–β, together with TNF–α, was reported to induce apoptosis in human hepatoma cells." (PMID 15540802, 2003).
hepatocellular carcinoma (continued). "Hepatocellular carcinoma (HCC) is another inflammation-driven cancer, where inflammatory cytokines such as TNF-α and IL-6 activate downstream targets including NF-κB, JNK, and STAT3, thereby promoting tumorigenesis." (PMID 40051564, 2025). "Studies using co‐culture models of hepatocellular carcinoma (HCC) and ECs reveal that endothelial cells trigger an inflammatory response in HCC cells, leading to an upregulation of the TNF signaling pathway." (PMID 40150879, 2025). "M2-like macrophages induce EMT and enhance tumor resistance in hepatocellular carcinoma (HCC) by secreting TNF-α via the Wnt/β-catenin pathway." (PMID 38341519, 2024). "Studies have shown that lipopolysaccharides (LPS) can contribute to hepatocellular carcinoma (HCC) development by inducing IL-6 and TNF-α production from the hepatic progenitor cells." (PMID 38463942, 2024). "In comparison with siglec-10+ NK cells found in hepatocellular carcinoma (HCC) cells, siglec-10− NK cells secreted lower levels of TNF-α, IFN-g, perforin, and granzyme." (PMID 38137380, 2023). "We subjected mice engineered to develop hepatocellular carcinoma (HCC), to treatment with tumor necrosis factor alpha (TNFα) conjugated to a CSG peptide (CSGRRSSKC)." (PMID 35273916, 2022). "In addition, we found higher levels of the TNF-α gene, p-p65, and IL-17 protein expression in HepG2 cells, which may result from HepG2 being a hepatocellular carcinoma cell, with inherently high levels of inflammation." (PMID 35684158, 2022). "ROS-dependent lncRNA AX800134 was upregulated by TNF-α in hepatocellular carcinoma (HCC), which was elucidated to be responsible for the growth of cancer cells." (PMID 35081965, 2022). "Indeed, previous studies also revealed such a discrepancy among Asian and non-Asian ethnicity regarding the TNF-308 G/A polymorphisms in hepatocellular carcinoma risk." (PMID 34900737, 2021). "In hepatocellular carcinoma (HCC), TNFα-induced NF-kB signaling downregulates HNF1α, thereby inhibiting miR-194, and results in tumorigenesis." (PMID 34771521, 2021). "Lymphotoxin β receptor (LTBR), a member of the tumor necrosis factor (TNF)/TNF receptor superfamily, significantly affects the activation and clonal expansion of CD8+ T cells and has been found to be associated with the development and progression of hepatocellular carcinoma." (PMID 34109216, 2021). "In addition, HIF1A-AS1 is overexpressed in hepatocellular carcinoma and supports cell survival, whereas this lncRNA was reported to promote apoptotic cell death induced by tumor necrosis factor-α in Kupffer cells, suggesting a possibility of context-specific functions of other lncRNAs." (PMID 34298879, 2021). "This is particularly shown in hepatocellular carcinoma (HCC) whereby, the increased hepatic mRNA levels of FNDC5/irisin in HCC patients correlated with increased expression of proinflammatory markers, such as IL-6 and TNF-α." (PMID 33614663, 2021). "Adipose tissue is considered to be an endocrine organ that secretes proinflammatory cytokines such as tumor necrosis factor, and they are closely related to the progression of hepatocellular carcinoma (HCC)." (PMID 33294448, 2020). "Overexpression of TUC339 in hepatocellular carcinoma (HCC) cells suppressed the expression of proinflammatory factors, such as IL-1β and TNF-α, and knockdown of TUC339 obtained an opposite effect." (PMID 32190702, 2020). "In hepatocellular carcinoma (HCC), tumour-derived monocytes have been found to induce dysfunctions in NK cells that were impaired in their ability to produce TNFα and IFNγ." (PMID 33569050, 2020). "Therefore, we concluded that preoperative sera IL6, IL8, and TNF-α may predict the postoperative recurrence of hepatocellular carcinoma." (PMID 31781194, 2019). "From the previous report, TNF-α could induce the upregulation of FoxM1 in hepatocellular cancers." (PMID 29554906, 2018).